AQP8 (aquaporin 8)
Description:
Channel that allows the facilitated permeation of water and uncharged molecules, such as hydrogen peroxide and the neutral form of ammonia (NH3), through cellular membranes such as plasma membrane, inner mitochondrial membrane and endoplasmic reticulum membrane of several tissues. The transport of the ammonia neutral form induces a parallel transport of proton, at alkaline pH when the concentration of ammonia is high (By similarity). However, it is unclear whether the transport of proton takes place via the aquaporin or via an endogenous pathway (By similarity). Also, may transport ammonia analogs such as formamide and methylamine, a transport favourited at basic pH due to the increase of unprotonated (neutral) form, which is expected to favor diffusion. Does not transport urea or glycerol. The water transport mechanism is mercury- and copper-sensitive and passive in response to osmotic driving forces. At the canicular plasma membrane, mediates the osmotic transport of water toward the bile canaliculus and facilitates the cAMP-induced bile canalicular water secretion, a process involved in bile formation. In addition, mediates the hydrogen peroxide release from hepatocyte mitochondria that modulates the SREBF2-mediated cholesterol synthesis and facilitates the mitochondrial ammonia uptake which is metabolized into urea, mainly under glucagon stimulation. In B cells, transports the CYBB-generated hydrogen peroxide from the external leaflet of the plasma membrane to the cytosol to promote B cell activation and differentiation for signal amplification (By similarity). In the small intestine and colon system, mediates water transport through mitochondria and apical membrane of epithelial cells (By similarity). May play an important role in the adaptive response of proximal tubule cells to acidosis possibly by facilitating the mitochondrial ammonia transport.
Synonyms: AQP-8
Tractability: Antibody: UniProt places it where antibodies can reach, with high confidence; its Gene Ontology location is reachable by antibodies, with high confidence; UniProt predicts a signal peptide or a membrane-spanning region.
Gene: Protein-coding gene on chromosome 16 (25,215,731 to 25,228,932, forward strand). Ensembl gene ENSG00000103375.
Subcellular location: Cell membrane; Mitochondrion inner membrane; Apical cell membrane; Basolateral cell membrane; Smooth endoplasmic reticulum membrane
Pathways (Reactome):
Cellular responses to stimuli: Detoxification of Reactive Oxygen Species
Developmental Biology: Developmental Lineage of Pancreatic Acinar Cells
Transport of small molecules: Passive transport by Aquaporins
Gene Ontology:
Molecular function: methylammonium channel activity; protein binding; water channel activity; ammonium channel activity; urea channel activity; channel activity
Biological process: ammonium transmembrane transport; cellular detoxification; cellular response to cAMP; hydrogen peroxide transmembrane transport; methylammonium transport; regulation of cholesterol biosynthetic process; water transport; ammonium import across plasma membrane; B cell differentiation; transepithelial water transport; urea transport; methylammonium transmembrane transport; one-carbon compound transport; transmembrane transport; urea transmembrane transport
Cellular component: apical part of cell; intracellular canaliculus; mitochondrial inner membrane; plasma membrane; apical plasma membrane; basolateral plasma membrane; brush border membrane; intracellular vesicle; mitochondrial membrane; mitochondrion; smooth endoplasmic reticulum; smooth endoplasmic reticulum membrane; membrane
Genetic constraint (gnomAD): Loss-of-function variants: 14 observed, 26.72 expected, observed/expected ratio (o/e) 0.52, 90% interval 0.34 to 0.82. The upper end of that interval is the gene's LOEUF score, 0.82, which puts it in group 3 of 6, group 1 being the genes least tolerant of losing a copy. Missense variants: 289 observed, 340.38 expected, observed/expected ratio (o/e) 0.85, 90% interval 0.77 to 0.94. Synonymous variants: 129 observed, 151.66 expected, observed/expected ratio (o/e) 0.85, 90% interval 0.74 to 0.98.
Homologues: Orthologues: chimpanzee AQP8 (99% identical), macaque AQP8 (96% identical), dog AQP8 (87% identical), pig AQP8 (84% identical), rabbit AQP8 (82% identical), guinea pig AQP8 (79% identical), mouse Aqp8 (76% identical), rat Aqp8 (75% identical), tropical clawed frog aqp8 (66% identical), zebrafish aqp8a.1 (49% identical), Caenorhabditis elegans aqp-4 (32% identical), Drosophila melanogaster Eglp3 (27% identical), and 3 more. Paralogues in human: AQP5 (30% identical), AQP2 (30% identical), MIP (28% identical), AQP6 (27% identical), AQP1 (26% identical), AQP3 (26% identical), AQP4 (25% identical), AQP9 (25% identical), AQP7 (24% identical), AQP10 (23% identical), AQP7B (23% identical).
Diseases named in the same sentence as AQP8 in open-access papers:
AQP8 is named in the same sentence as 83 diseases in open-access papers, as found by Europe PMC text mining. Sharing a sentence is not in itself a finding about the gene and the disease. The quoted sentences say what the papers report.
colorectal cancer (13 papers, 2012 to 2026). A primary or metastatic malignant neoplasm that affects the colon or rectum. "Different investigations concluded that AQP8 diminished expression is remarkably linked to the development of colorectal cancer, cervical cancer, and pancreatic ductal cancer." (PMID 37954103, 2023). "They affect AQP2, AQP5 and AQP8, where they are associated with nephrogenic diabetes insipidus, keratoderma and colorectal cancer, respectively." (PMID 29799470, 2018). "The down expression of five genes (SLC26A3, GUCA2A, CLCA4, CLCA1, and AQP8) was significantly associated with poor overall survival in colorectal cancer adenocarcinoma patients, and patients with lower expression levels of CLCA1 had poorer disease-free survival rates." (PMID 35693937, 2022). "Underexpression of AQPs for AQP8 has been observed in colorectal cancer, AQP8 and AQP9 in hepatocellular carcinoma, AQP4 in pleural mesothelioma, and AQP1 in cervical cancer." (PMID 40100646, 2025). "This study aimed to detect the expression of AQP5 and AQP8 in clinical samples of colorectal cancer and analyze the correlations of their expression with the clinicopathological features of colorectal cancer." (PMID 23148732, 2012). "By contrast, AQP8 mRNA was abundant in adjacent normal colon tissue but undetectable in colorectal carcinoma tissue." (PMID 23148732, 2012). "We employed RT-PCR and immunohistochemical methods to detect the expression of AQP5 and AQP8 in clinical samples of colorectal carcinoma and the paraneoplastic normal colonic tissues." (PMID 23148732, 2012). "By contrast, AQP8 was mainly expressed in paraneoplastic normal tissues and barely expressed in colorectal carcinoma cells." (PMID 23148732, 2012). "However, its mammalian ortholog, AQP8, was shown to inhibit colorectal cancer cell lines in vitro, suggesting cell- and context-dependent function of AQP8 in the regulation of cell migration." (PMID 39977018, 2025). "Over-expressed AQP8 in colorectal cancer (CRC) cells can inhibit the PI3K/Akt signaling transduction, which may have a similar effect in OA, and in concert with BRD7, leads to downregulation of PI3K activity in OA." (PMID 37378023, 2023). "However, the expression of AQP5 and AQP8 in colorectal cancer and the clinical significance remain unexplored." (PMID 23148732, 2012). "The clinical significance of AQP5 and AQP8 in colorectal carcinoma remains largely unexplored." (PMID 23148732, 2012). "Indeed, AQP8 may inhibit colorectal cancer growth and metastasis by decreasing PI3K/AKT signaling and PCDH7 expression; thus, AQP8 status in colorectal carcinoma has a potential clinical significance." (PMID 32457800, 2020). "These images showed that AQP8 and NR5A2 exhibited low staining intensity in colorectal cancer tissues, whereas SCD and TIMP1 showed high staining intensity." (PMID 41438584, 2026). "AQP8 overexpression in the colorectal cancer cell lines SW480 and HT-29 inhibited the growth and invasion of colorectal cancer cells by inactivating the PI3K/AKT signaling pathway and inhibiting PCDH7 expression." (PMID 37280594, 2023). "Mechanistically, the overexpression of AQP8 inhibits the expression of PCDH7 through the PI3K/AKT signaling pathway, thereby inhibiting the growth and metastasis of colorectal cancer cells." (PMID 32462020, 2020). "The OS analysis of 10 core genes was performed by using the GEPIA tool website, and the results show that low expressions of AQP8, ZG16, CXCL3, and CXCL8 may predict poor survival outcome in colorectal cancer." (PMID 32462020, 2020). "The results of OS analysis have shown that low expressions of AQP8, ZG16, CXCL3, and CXCL8 may predict poor survival outcome in colorectal cancer." (PMID 32462020, 2020). "Gene Expression Profiling Interactive Analysis (GEPIA) overall survival (OS) analysis has shown that low expressions of AQP8, ZG16, CXCL3, and CXCL8 may predict poor survival outcome in colorectal cancer." (PMID 32462020, 2020).
colorectal cancer (continued). "Gene Expression Profiling Interactive Analysis (GEPIA) overall survival (OS) has shown that low expressions of AQP8, ZG16, CXCL3, and CXCL8 may predict poor survival outcome in colorectal cancer." (PMID 32462020, 2020). "The first is that AQP8 is not expressed in patients with colorectal carcinoma." (PMID 28229027, 2017).
cholestasis (10 papers, 2018 to 2026). Impairment of the bile flow caused by obstruction within the liver, or outside the liver in the bile duct system. "The association between downregulation of canalicular AQP8 and decreased canalicular osmotic water permeability suggests relevance for AQP8 in cholestasis." (PMID 37681902, 2023). "The reduced AQP8 expression in turn causes reduced water permeability of hepatocytes, which can result in reduced bile formation and aggravates cholestasis." (PMID 29449936, 2018). "Research has shown that endotoxin decreases AQP8 expression in rat hepatocytes, worsening cholestasis." (PMID 40115259, 2025). "The reduced bile flow, biliary sludge, and cholestasis accompanying human hepatic ischemia and hypoxia were shown to involve a reduction in the hepatocyte AQP8 protein through a mechanism occurring at a post-translational level." (PMID 39596202, 2024). "In cholestasis, downregulation of AQP8 by TNF-α after LPS stimulation reduces water permeability in hepatocytes, impairing bile formation and exacerbating cholestasis." (PMID 39544938, 2024). "The role of AQP8 in cholestasis is indicated by the downregulation of canalicular AQP8 and decreased canalicular osmotic water permeability." (PMID 39596202, 2024). "Previous studies have demonstrated that AQP8 expression is downregulated in liver diseases such as cholestasis, hepatic steatosis, and NAFLD, leading to hepatocyte swelling and lipid accumulation due to impaired water transport." (PMID 39459500, 2024). "Dysregulated expression of AQP8 at the canalicular side of hepatocytes contributes to the development of cholestasis in several experimental models of cholestasis including extrahepatic obstructive cholestasis, estrogen-induced cholestasis and sepsis-induced cholestasis." (PMID 37681902, 2023). "In cholestasis AQP8 might play a role as it is downregulated after LPS stimulation in hepatocytes via TNF-α." (PMID 29449936, 2018). "Finally, hepatic Aqp8 expression was markedly suppressed in chronic alcohol feeding models, suggesting impaired bile flow, which may contribute to cholestasis and promote liver injury." (PMID 41522337, 2026). "Use of experimental models of cholestasis including extrahepatic obstructive cholestasis, estrogen-induced cholestasis, and sepsis-induced cholestasis suggest that the dysregulated expression of AQP8 at the canalicular side of hepatocytes contributes to the development of cholestasis." (PMID 39596202, 2024). "Additionally, AQP8 and AQP9 expression is reduced in the livers of rats with ligated bile ducts, whereas increased AQP1 expression alleviates cholestasis." (PMID 40115259, 2025). "Here, a low iodine diet reduced hepatic Aqp9 expression, and a lithogenic diet increased hepatic Aqp8 expression only in female but not male C57BL/6J mice which could protect the livers of female mice to hepato-steatosis and cholestasis." (PMID 36293210, 2022).
colitis (8 papers, 2008 to 2025). Inflammation of the colon. "That study also suggested thatAQP8 in particular might be required to maintain an absorptive phenotype in thecolon, since loss of AQP8 in the DSS model of colitis correlated with a switch to asecretory phenotype." (PMID 25793528, 2015). "AQP3 and AQP8 have been reported to be down-regulated in rats with colitis and ETEC induced diarrhea." (PMID 37180229, 2023). "Chemical induction of colitis by treatment with dextran sulfate sodium results in substantial downregulation of carbonic anhydrases CA I and CA IV and aquaporins Aqp4 and Aqp8." (PMID 18680595, 2008). "Instead, in a drug-induced colitis mouse model, mimicking human Crohn’s disease, AQP8 expression is downregulated as inflammation and injury increases, a fact that may be better interpreted in terms of its peroxiporin activity." (PMID 30463362, 2018). "On the other hand, in 2,4,6-trinitrobenzene sulfonic acid (TNBS)-induced colitis model, which mimics human Crohn’s disease, AQP8 expression is downregulated with the increase of inflammation and injury, which indicates that AQP8 is possibly involved in inflammatory bowel disease." (PMID 30336596, 2018). "Moreover, the abnormal regulation of fluid and electrolyte flux in IBD patients and in a murine colitis model may be associated with significant reductions in AQP4 and AQP8 mRNA expression in the colon." (PMID 27589719, 2016). "AQP3 and AQP8 were detected in the colon of Sprague Dawley rats, and their expression was decreased in 2,4,6-trinitrobenzene sulfonic acid (TNBS)-induced colitis, a model that mimics human Crohn’s disease histopathology." (PMID 33673336, 2021). "A murine model of colitis induced by dextran sulphate presented decreased AQP4 and AQP8 gene and protein levels that correlated with significant alteration in colonic fluid secretion." (PMID 33673336, 2021). "In the trinitro-benzene-sulfonic acid-induced colitis of rats, the mRNA and protein expressions of AQP3 and AQP8 were also downregulated in the ileum and colon." (PMID 27589719, 2016). "However, analogously to AQP8, downregulation of AQP3 levels was observed in the colon of Crohn’s disease and ulcerative colitis patients and in drug-induced colitis as the signs of intestinal inflammation and injury progress." (PMID 30463362, 2018).
colon cancer (8 papers, 2008 to 2023). "Clinical trials indicated high expression of AQP8 was associated with better prognoses and overall survival in colon cancer." (PMID 37760476, 2023). "Through the analysis of each gene on the prognosis of colon cancer through the GEPIA online analysis website, it was found that the expression levels of AQP8, CXCL8, and ZG16 genes were remarkably associated with colon cancer prognosis (P < 0.05)." (PMID 37954103, 2023). "Overexpression of AQP8 has been linked with reduced migration and invasion through inhibition of PI3/Akt in colon cancer, and pathologies such as epithelial ovarian, cervical, colorectal, and liver cancers also have been associated with altered AQP8 expression." (PMID 37760476, 2023). "The expression levels of the two Hub genes, AQP8 and ZG16, whose expression levels were significantly associated with the prognosis of colon cancer, were examined in human normal epithelial cells (NCM460) and colon cancer cells (SW48 and HT29)." (PMID 37954103, 2023). "However, it was reported that AQP8 expression is lower in colon cancer tissues than in normal colon tissues." (PMID 37280594, 2023). "Notably, a number of genes profoundly downregulated in susceptible FVB mice, such as Slc26a3 (Dra), Aqp8, CAIV, and Slc5a8 (Ait), are also implicated in the development of colonic tumors." (PMID 18680595, 2008). "However, the clinical importance of AQP8 in colon cancer remains undetermined." (PMID 28229027, 2017).
ulcerative colitis (8 papers, 2013 to 2023). An inflammatory bowel disease involving the mucosal surface of the large intestine and rectum. "For example, AQP8 downregulation was described in human Crohn’s disease and ulcerative colitis biopsies." (PMID 34360801, 2021). "AQP4, AQP7 and AQP8 mRNAs were all detected in both normal colons and in the colons of patients with ulcerative colitis, Crohn’s disease and infectious colitis." (PMID 27589719, 2016). "Alater study also reported a decrease in AQP8 mRNA levels in ileal tissue from IBDpatients (including ulcerative colitis patients), but found a contrasting increasein AQP8 levels in colonic tissue from these patients." (PMID 25793528, 2015). "AQP8 expression decreased in the colon of patients with ulcerative colitis, and this reduction appears to correlate with disease activation in patients with diarrhea-predominant irritable bowel syndrome." (PMID 24205035, 2013). "AQP8 downregulation was also described in human Crohn’s disease and ulcerative colitis biopsies, suggesting that AQP8’s role as a H2O2 channel is involved in metabolism, and its downregulation may represent a defense mechanism against severe oxidative stress." (PMID 33673336, 2021). "However, AQP8 mRNA and protein levels were significantly enhanced in the colon of ulcerative colitis and paraneoplastic normal tissues." (PMID 28122499, 2017). "The reduced mRNA expression of several AQPs (AQP1, AQP3, AQP7 and AQP8) in human intestinal mucosa has been demonstrated at the early stage of inflammatory bowel diseases (IBD), including Crohn’s disease and ulcerative colitis." (PMID 27589719, 2016). "From biopsy samples of patients, AQP8 expression was permanently downregulated in ulcerative colitis patients compared to noninflammatory bowel disease subjects, which may be involved in pathological abnormalities in absorptive function in the intestinal tract." (PMID 34540996, 2021).